BRCA2 (BRCA2 DNA repair associated)
Diseases named in the same sentence as BRCA2 in open-access papers (continued):
Sharing a sentence is not in itself a finding about the gene and the disease.
pancreatic cancer (continued). "The American Society for Gastrointestinal Endoscopy recommends screening individuals with an increased risk of pancreatic cancer due to genetic susceptibility, including BRCA2 and BRCA1 gene mutations, using imaging methods—EUS, MRI, or a combination of both methods." (PMID 37509296, 2023). "In F1CDx, BRCA2 mutations were more common in the prostate than in breast or pancreatic cancers." (PMID 37916805, 2023). "Mutations in BRCA2 appear to be more common in pancreatic cancer." (PMID 36902416, 2023). "As expected, BRCA1/2 variants comprised the majority of the tumor/germline variants in patients with stage III/IV breast, ovarian and pancreatic cancers; however, we also detected tumor/germline BRCA2 variants in atypical cancers such as colorectal, esophagogastric, NSCLC, and sarcoma." (PMID 36261688, 2023). "Mutations in BRCA2 also cause a 5–10% lifetime risk for pancreatic cancer, while BRCA1 carriers might have two to four times risks compared to non-carriers." (PMID 38274092, 2023). "A BRCA2 pathogenic variant was detected in an unselected pancreatic cancer patient (1/150; 0.7%)." (PMID 37951914, 2023). "Further, we show that POLQ inhibition causes the accumulation of cytosolic DNA to activate the cyclic GMP-AMP synthase–stimulator of interferon genes (cGAS-STING) signaling pathway in BRCA2-deficient pancreatic tumors, thus enhancing intratumoral T cell infiltration." (PMID 36976649, 2023). "Furthermore, in another family with 10 healthy collateral relatives of a proband with pancreatic cancer at the age of 58 years, we tested two variants: BRCA2 c.8487+1G>A and ATM c.6095G>A." (PMID 38136276, 2023). "To evaluate if BET inhibition is an effective therapeutic approach for BRCA2-deficient pancreatic cancer in vivo, we subcutaneously injected KPC-mT3 cells into immunocompromised athymic nu/nu mice, and administered either with vehicle or JQ1 (50 mg/kg) via intraperitoneal injection." (PMID 37735513, 2023). "Current screening, often with high-cost diagnostics such as magnetic resonance imaging (MRI) or endoscopic ultrasonography (EUS), is limited to people with a family history of pancreatic cancer or genetic risk factors (BRCA2 mutation, Lynch syndrome, or familial adenomatous polyposis)." (PMID 36980796, 2023). "Interestingly, inactivation of both alleles of Brca2 gave rise to less pancreatic tumors and PanIN lesions than wild type Brca2 but caused more pancreatic insufficiency due to inflammatory degeneration of pancreatic parenchyma into adipose tissue." (PMID 35163129, 2022). "Thus, individuals with a pathogenic BRCA2 or PALB2 variant also have a significantly increased risk for pancreatic cancer." (PMID 36292468, 2022). "However, even using a false discovery rate adjustment, all the observed associations for BRCA2 carriers and the pancreatic cancer association for BRCA1 carriers had false discovery rates < 0.05." (PMID 35077220, 2022). "Early or late inactivation of the second allele of the wild-type BRCA2 may affect phenotypes of human pancreatic tumors." (PMID 35163129, 2022). "The most common cause of hereditary pancreatic cancer is a germline mutation in BRCA2." (PMID 35163129, 2022). "BRCA1 and BRCA2 genes are part of the homologous DNA repair pathway (HR), and the mutations in these genes are powerful contributors to the development of several cancers, including breast, prostate, ovarian, and pancreatic cancers." (PMID 36556296, 2022). "By the way, it was reported that the mutations in BRCA2 significantly increase the risk of pancreatic cancer; whether it is associated with EMT is a question that needs to be further explored." (PMID 35444701, 2022). "Homozygous Brca2 inactivation caused more pancreatic tumors than heterozygous Brca2 inactivation." (PMID 35163129, 2022). "BRCA2-mutated patients have a 3.5-6-fold higher risk for developing pancreatic cancer." (PMID 35228986, 2022).
pancreatic cancer (continued). "Since BRCA1/BRCA2 are frequently mutated in PanNETs and are significant predictors of survival outcome in pancreatic cancer patients, we analyzed if BRCA1/2 CNVs could impact the PFS in PanNETs patients." (PMID 36140756, 2022). "KRAS mutations are observed in 94% and BRCA2 mutations in 6% of patients with pancreatic cancer." (PMID 35666369, 2022). "BRCA1 or BRCA2 mutation can increase biliary and pancreas cancer incidence by around threefold." (PMID 34577828, 2021). "There is also some evidence that knowledge of BRCA1 or BRCA2 mutation may direct personalized treatment of pancreatic cancer." (PMID 33920818, 2021). "For example, approximately 1% of individuals of Ashkenazi Jewish decent have a pathogenic germline BRCA2 variant (c.6174delT) that is associated with a 10-fold increased risk of pancreatic cancer, as well as an increased risk of other cancers including cancers of the breast, ovary, and prostate." (PMID 33555482, 2021). "Moreover, the relative risk (RR) and cumulative incidence of pancreatic cancer for germline BRCA2 pathogenic variants are 3.5–10 and 2%–7%, and for germline BRCA1 pathogenic variants, 2.26 and 1%–3%, respectively." (PMID 34476650, 2021). "In addition, pancreatic cancer occurred more frequently in families carrying a pathogenic BRCA1 variant along with BRCA2 c.9976A>T (double heterozygotes) (0.5) compared to wild type (0.04) and pathogenic BRCA1 carrier families (0.06)." (PMID 33672545, 2021). "However, she also received counseling for management of risk for other malignancies including colon cancer, pancreatic cancer, and melanoma based on the presence of concurrent pathogenic mutations in BRCA2 and CHEK2." (PMID 33507482, 2021). "Individuals with a family history of pancreatic cancer, obesity, and diabetes were also found to be more prone to pancreatic cancer, pointing to the fact that genetic susceptibility and family history do play a role in tumor development, the most common mutations cited being BRCA2 and PALB." (PMID 34066284, 2021). "Two patients with BRCA2 P/LP variants were sporadic cases of adenocarcinoma of pancreatic cancer." (PMID 33649982, 2021). "The most commonly mutated genes in familial pancreatic cancer are BRCA2, CDKN2A, BRCA1, and PALB2." (PMID 34712667, 2021). "BRCA2 germline mutation is also one of the most common causes of familial pancreatic cancer." (PMID 34205170, 2021). "BRCA2 mutations are highly associated with familial and sporadic pancreatic cancers." (PMID 32774122, 2020). "Interestingly both, BRCA2-proficient BxPC3 and Capan-1 pancreatic cancer cells with BRCA2-deficiency turned out to be more sensitive to SOBP proton irradiation when compared to X-ray photon irradiation." (PMID 32260562, 2020). "Increased risks for prostate and pancreatic cancer occur in families with the BRCA2 mutation." (PMID 32349445, 2020). "Among the inherited risk factors for pancreatic cancer are genomic mutations such as BRCA2, which confers a 3.5-fold higher risk in carriers, with the probability of a germline mutation between 6 and 12% in PDAC patients with a first-degree relative diagnosed with PDAC9." (PMID 33077732, 2020). "The ESMO clinical practice guidelines for cancer prevention and screening in BRCA mutation carriers state that annual screening for pancreatic cancer may be considered in BRCA2 mutation carriers." (PMID 32655641, 2020). "Among familial pancreatic cancer patients, germline BRCA2 mutations have been observed in 5–17%, especially in the Ashkenazi Jewish population, in which there are 10% of unselected, apparently sporadic, pancreatic cancers related to germline BRCA mutations." (PMID 32122376, 2020). "Additionally, BRCA2 mutations are present in 7% of pancreatic cancers irrespective of familial history, and accounting for ~10% of hereditary pancreatic cancers." (PMID 32481735, 2020).
pancreatic cancer (continued). "These preclinical results indicate that DNA damaging agents are effective and could be particularly useful in the treatment of PALB2-, BRCA1- or BRCA2- deficient pancreatic tumors, which is reminiscent of human cancers defective for ‘BRCAness’." (PMID 31877165, 2019). "BRCA variants may be associated with other cancers such as pancreas and colon cancer, in particular BRCA2 variants are associated to a relatively low increase in risk of pancreas cancer." (PMID 31888263, 2019). "After discovery of BRCA2 in 1995, when a homozygous deletion lying within 13q12.3 where the BRCA2 gene resides was identified in a human pancreatic cancer, more germline BRCA2 mutations were found in pancreatic cancer patients." (PMID 31877165, 2019). "As shown repeatedly in both ovarian and breast cancer, the commended POLO trial has strengthened the encouragement for PARP inhibition in solid tumors, now likely setting a new standard of care in pancreatic cancer for those with germline BRCA1 or BRCA2 mutations." (PMID 32030362, 2019). "Moreover, 11 of these individuals without a report of pancreas screening on file harbored a deleterious BRCA1 or BRCA2 mutation and a family history of pancreatic cancer, including one individual with six second degree relatives with the disease." (PMID 32601617, 2019). "In addition, these compounds exacerbated DNA damage and cell death in response to the PARP inhibitor olaparib in BRCA2-deficient Capan-1 cells and cooperated with gemcitabine to the killing of pancreatic cancer cells." (PMID 31591350, 2019). "In a logistic regression model adjusted for age at diagnosis and family history of cancer, ATM and BRCA2 mutations were associated with personal history of breast or pancreatic cancer, whereas PALB2 mutations were associated with family history of breast or pancreatic cancer." (PMID 31497750, 2018). "Thus, it was shown that BRCA2 mutation induces pancreatic tumors through the induction of excessive reactive nitrogen species, such as nitrites, which induce massive DNA damage." (PMID 29156578, 2017). "Although chronic pancreatitis is an important risk factor for pancreatic cancer development most of the mutated genes found to contribute to pancreatic cancer susceptibility when defective are classic tumor suppressor genes, such as BRCA2, ATM, PALB2, p16, and STK11." (PMID 28881607, 2017). "It has been reported that germline mutations in BRCA1 and BRCA2 predispose to pancreatic cancer." (PMID 29069866, 2017). "Heritable, germline mutations in p16, BRCA2, and other genes appear to be associated with a total of 5%-10% of all pancreatic cancers, and penetrance of these mutations for the disease may be fairly low." (PMID 28966726, 2017). "In their high-risk pancreatic cancer families, 3% carried BRCA2 mutations." (PMID 29069866, 2017). "Other studies have shown that BRCA2 causes 3–5% pancreatic cancers in population and clinic-based cohorts, thus indicating that this gene is the most common high-penetrant cause of pancreatic cancer." (PMID 29156578, 2017). "Germline variants on BRCA2 have also been identified to be associated with pancreatic cancer risk." (PMID 28415599, 2017). "Several heritable, germline mutations in p16 and/or BRCA2 may be associated with the development of pancreatic cancer." (PMID 28966726, 2017). "BRCA2 mutation is also associated with prostate and pancreatic cancers and melanoma." (PMID 27488020, 2016). "Family history of pancreatic cancer was most prominent in patients with BRCA2 germline mutations." (PMID 27069714, 2016).
pancreatic cancer (continued). "A recent study suggested that BRCA2 mutations could account for 6% of moderate and high-risk pancreatic cancer families." (PMID 25961039, 2015). "Furthermore environmental and genetic factors have been proposed as causes of the pancreatic cancer with the genetic factor of particular importance believed to be the BRCA2 gene." (PMID 26236408, 2015). "Although up to 20% of hereditary pancreatic cancer cases are associated with germline mutations in BRCA2, CDKN2A, PRSS1, STKI1, or MMR genes, the major underlying gene defects are still unknown." (PMID 24616882, 2014). "Although several important and high-penetrance genes associated with increased risk of pancreatic cancer have been identified, including BRCA2 and PALB2, it is clear that most cases of pancreatic cancer that demonstrate familial clustering are not explained by known genetic syndromes." (PMID 24624093, 2014). "Interestingly, mutations in BRCA2, which plays a key role in initiating HR, are known to increase the risk of pancreatic cancer." (PMID 24901438, 2014). "Our case highlights the facts (i) that pancreatic carcinomas belong to the tumor spectrum of patients with the BRCA2-associated hereditary breast and ovarian cancer syndrome (HBOC) and (ii) that tumors of the pancreas can represent the first or even the only manifestation of HBOC." (PMID 24959366, 2014). "A significant association between BRCA2 mutation and pancreatic cancer has also been demonstrated." (PMID 23202913, 2012). "Thus, identification of the BRCA2 gene in a patient would be a reason to screen for an associated pancreatic cancer, especially in the Ashkenazi Jewish population who have a high rate of BRCA2 mutations." (PMID 23202913, 2012). "This comprehensive sequence analysis of a BRCA2-deficient pancreatic cancer cell line provides a valuable resource that will, in combination with large-scale genome resequencing of patient tumour samples, facilitate the identification of new biomarkers and targets for therapy." (PMID 21750719, 2011). "Mutations of BRCA2 were implicated in cancers of the pancreas and breast." (PMID 19826425, 2009). "Several genetic syndromes such as familial pancreatitis, Peutz-Jeghers syndrome, and familial atypical multiple mole melanoma are associated with an increased risk of pancreatic cancer, in addition to mutations in the tumor suppressor gene BRCA2 and several DNA mismatch repair genes." (PMID 19956730, 2009). "In a similar manner, mutations in BRCA1 and BRCA2 may explain in part the cluster seen between prostate, breast, ovarian, and possibly pancreatic cancer." (PMID 15630470, 2004). "Indeed, carriers of BRCA2 mutations exhibit a 3.5–5.8-fold increased risk of developing pancreatic cancer compared to the general population, and mutations in the BRCA1 gene, encoding a crucial protein involved in DNA repair, are also associated with an elevated risk of pancreatic cancer." (PMID 39064499, 2024). "The observed dichotomy in precursor lesions between the Brca1-deficient and Brca2-deficient tumors and the mixture of both in Palb2 deficient tumors might provide insights into mechanisms underlying the higher pancreatic cancer incidence and aggressiveness in BRCA2 vs BRCA1 mutation carriers." (PMID 31877165, 2019). "Moreover BRCA1 and BRCA2 mutations resulting in DNA damage repair deficiency and increasing especially the risk for breast and ovarian cancer are the most common causes of familial pancreatic cancer." (PMID 31540286, 2019). "Additionally, BRCA2 mutations occur in 3.6–10% of all sporadic pancreatic cancers." (PMID 27630665, 2016). "Therefore, we asked whether radiation sensitivity of pancreatic cancers developing in individuals with germline BRCA2 mutations can be enhanced by agents that inhibit poly (ADP-ribose) polymerase (PARP)." (PMID 28033382, 2016).
pancreatic cancer (continued). "However, definitive evidence addressing the extent to which the lessons from GEMMs of Brca2‐deficient pancreatic cancers can be applied to human neoplasia awaits the results of more extensive genome sequencing studies on pancreatic cancer samples from patients harbouring germline BRCA2 mutations." (PMID 24268522, 2014). "Regarding pancreatic cancer, Olaparib is the only PARP inhibitor that has been FDA-approved for usage in patients with pancreatic cancers with BRCA1 or BRCA2 mutations." (PMID 40842586, 2025). "Therapeutic methods for pancreatic cancer patients with specific genetic mutations, such as BRCA1 or BRCA2 mutations and KRAS mutations, are currently being researched." (PMID 40948342, 2025). "It has been demonstrated that the risk of pancreatic cancer is increased in patients with loss-of-function BRCA1 and BRCA2 mutations." (PMID 40124650, 2025). "Histological analysis of mouse pancreatic tissues revealed that BRCA2 inactivation promoted the development of precancerous lesions and pancreatic tumors." (PMID 41155399, 2025). "A prior report documented coinheritance of APC and BRCA2 mutations in an individual with FAP and intraductal papillary mucinous neoplasm (IPMN), whose siblings also carrying both mutations developed pancreatic cancer." (PMID 39985003, 2025). "It has been shown that advanced pancreatic cancer with biallelic loss of BRCA1 and BRCA2 had a higher median tumor mutation burden than wild type tumors with the consequent possible higher sensitivity to ICIs." (PMID 40124650, 2025). "Germline pathogenic or likely pathogenic variants (PVs) in the BRCA1 and BRCA2 (BRCA) genes increase the relative and absolute risks of breast, ovarian, and other cancers, such as prostate and pancreatic cancer." (PMID 40772289, 2025). "The most common mutations were found in the BRCA1, BRCA2, ATM, PALB2, and CDKN2A genes, further highlighting the involvement of DDR-related genes in pancreatic cancer." (PMID 41155399, 2025). "Pancreatic cancer cases with BRCA2/PALB2 germline alterations exhibit a more enriched population of activated NK cells." (PMID 40830526, 2025). "In pancreatic cancer, cases with BRCA2/PALB2 germline alterations display higher IFN responses, encompassing both type I (α/β) and type II (γ)." (PMID 40830526, 2025). "Pancreatic cancer cases with BRCA2/PALB2 germline alterations demonstrate a more enriched B cell population, including memory B cells and naïve B cells, and the abundance of B cells shows a positive correlation with the HRD score." (PMID 40830526, 2025). "In recent years, multiple reports have shown that BRCA1, BRCA2 and PALB2 genes, which are known as “the core homologous recombination (HR) genes”, present germline mutations in up to 5% of patients with pancreatic cancer." (PMID 40124650, 2025). "Pancreatic cancer bearing BRCA2 p.I3169M fs*48 is sensitive to platinum and poly ADP ribose polymerase inhibitors." (PMID 37956396, 2024). "In cancers such as breast and pancreatic cancers, Signature 3 is strongly associated with germline or somatic BRCA1/BRCA2 mutations, which are well-established indicators for susceptibility to PARP inhibitors." (PMID 38939336, 2024). "Signature 3 has been previously reported in breast and pancreatic cancers and shows a strong association with germline and somatic BRCA1 and BRCA2 mutations, leading to defective homologous recombination repair of DNA double-strand breaks." (PMID 38315150, 2024). "Rucaparib was proven to be a safe and effective therapy for platinum-sensitive, advanced pancreatic cancer with a pathogenic variant in BRCA1, BRCA2, or PALB2." (PMID 38540206, 2024).